APOE (apolipoprotein E)
Diseases named in the same sentence as APOE in open-access papers (continued):
Sharing a sentence is not in itself a finding about the gene and the disease.
atherosclerosis (continued). "In addition to the spontaneous lesions induced by cholesterol diet feeding, we also examined whether apoE deficiency affects atherosclerosis induced by intimal injury." (PMID 39087075, 2024). "The primary aim of this study is to investigate whether SAA-mediated renal and vascular dysfunction can be ameliorated with 4-metT administered either before (prophylaxis) or after (therapeutic) supplementing recombinant SAA in atherosclerosis-prone apolipoprotein E-deficient (ApoE−/−) mice." (PMID 39063104, 2024). "Moreover, we demonstrate that genetic deficiency of the superoxide-generating enzyme Nox2 NADPH oxidase in mice haploinsufficient for the insulin receptor, and deficient in Apolipoprotein E leads to accelerated atherosclerosis and significant disruption of the architecture of the arterial wall." (PMID 39401163, 2024). "The second possibility is that enhanced atherosclerosis was essentially caused by increased number of apoB48-rich remnant lipoproteins possibly independent on the plasma levels of TC because both male and female apoE KO rabbits possessed higher contents of apoB48." (PMID 39087075, 2024). "However, HO-2 is also expressed in macrophages and the question about whether HO-2 is associated with atherosclerosis in apoE null (ApoE−/−) mice is poorly known." (PMID 36593926, 2023). "In addition, an inhibition of macrophage accumulation and reduction in oxidative stress were observed in the arterial tissues of mice in the HRW group, suggesting that drinking HRW may prevent atherosclerosis in ApoE-deficient mice." (PMID 37893190, 2023). "In addition to the activation and expansion of Tregs, we found HCW9302 also expanded the percentage of NK cells and reduced levels of CD4+ T cells in the blood and expanded M2 macrophage and MDSC levels in the atherosclerosis plaques of WD-fed ApoE deficient mice." (PMID 36761778, 2023). "The accelerated rate of atherosclerosis progression in ApoE KO mice minimizes other complications that may accompany atherosclerosis, making them ideal for confirming inflammatory biomarkers or Raman signals caused only by atherosclerosis." (PMID 37476064, 2023). "Animal studies using apolipoprotein E-deficient mice (ApoE(−/−)), an atherosclerosis mouse model, were used to determine whether the modulation of IAV-induced MCP-1 and IP-10 by metformin alleviates the underlying disease associated with influenza virus infection." (PMID 37810823, 2023). "Furthermore, epigenetic changes were also identified in several genes including RELA (RELA Proto-Oncogene, NF-KB Subunit), NOS3 (Nitric Oxide Synthase 3), KLF4 (KLF Transcription Factor 4) and APOE (Apolipoprotein E) that have been linked to progression of atherosclerosis." (PMID 37190071, 2023). "Furthermore, ApoE−/− mice deficient for glutathione peroxidase show increased atherosclerosis." (PMID 36497101, 2022). "Likewise, a totally deficient mitochondrial superoxide dismutase enzyme will make mice at a higher risk of endothelial dysfunction, and deletion of the glutathione peroxidase-1 will cause significant atherosclerosis and plaque formation leading to thrombosis in ApoE−/− mice." (PMID 35072089, 2022). "One study utilized the prevalent murine atherosclerosis model of ApoE-deficient mice and could herewith show that systemic MK administration augmented atherosclerotic lesion area, relative to saline-treated ApoE-deficient mice." (PMID 36204583, 2022). "Besides lipid metabolism and atherosclerosis, there might exist some other pathways underlying the relationships between APOE and risk of IS." (PMID 35154509, 2022).
atherosclerosis (continued). "Similarly, SELP (selectin-P) deficiency, one of the hepatic key regulators that in our study was found to be upregulated and linked to atherosclerosis signaling via TNFSF11, reduces atherosclerosis in combined P-selectin/ApoE knock-out mice vs. ApoE single knock-out mice." (PMID 35897797, 2022). "Some studies suggest that AMD and AD might be comorbid by showing that patients with AMD have an increased risk of AD, although this correlation becomes not significant when considering other factors such as age, presence of the apolipoprotein E (ApoE) allele, smoking, and atherosclerosis." (PMID 34439882, 2021). "Moreover, our results examining combined NEP inhibition and AT1R antagonism focus on atherosclerosis induced by infusion of AngII, which may differ from atherosclerosis in response to other stimuli (e.g., diet or ApoE deficiency)." (PMID 33707301, 2021). "Thus, we further investigated whether BBR-induced serum TMAO reduction was associated with the development of atherosclerosis in ApoE KO mice." (PMID 33863898, 2021). "However, the role of CCL3 in atherosclerosis may be dependent on the various receptors as deficiency of CCR1 in ApoE−/− mice fed a WD for 10 to 12 weeks led to accelerated atherosclerosis and greater plaque size and infiltration of T lymphocytes." (PMID 33503867, 2021). "E3L.CETP mice, due to their genetic APOE*3Leiden mutation, have an impaired clearance of apoB-containing lipoproteins, thereby mimicking the slow clearance observed in humans and resulting in a mouse model that develops hyperlipidemia and atherosclerosis upon saturated fat and cholesterol feeding." (PMID 33658534, 2021). "In addition, by depleting NK cells by anti–GM1 antibodies or transferring NK cells in atherosclerosis-prone ApoE-deficient mice, NK cells were demonstrated to play a protective role in the development of atherosclerosis, possibly via secretion of the cytotoxic molecules perforin and granzyme B." (PMID 33717101, 2021). "Thus, we evaluated the regulatory effects of acacetin in maintaining endothelial cell function and further investigated whether the flavonoid could attenuate atherosclerosis in apolipoprotein E deficiency (apoE−/−) mice." (PMID 33241629, 2021). "In apolipoprotein E-deficient (Apoe−/−) mice, a 1 week nanoimmunotherapy treatment regimen achieved significant anti-inflammatory effects, due to the reduced migration capacity of plaque monocytes; this highlights the translational potential of this strategy for the treatment of atherosclerosis." (PMID 33924893, 2021). "The association between ε2 and ε4 alleles in the APOE gene with increased risk of atherosclerosis, a chronic disease of inflammation and hyperlipidemia, in a manner that is independent of plasma lipid levels, suggested that apoE2 and apoE4 expression may elevate inflammatory response directly." (PMID 34425108, 2021). "Moreover, in a mouse model for atherosclerosis, namely in apolipoprotein E (ApoE)-deficient mice, cholesterol deposits and local dermal inflammation were observed to coincide with skin resident dendritic cells possessing a systemically reduced migratory behavior." (PMID 32411706, 2020). "Moreover, in the study of atherosclerosis, associated with infection of Porphyromonas gingivalis that causes periodontitis, circadian clock disruption enhanced atherosclerosis progression in Bmal1−/− ApoE−/− mice." (PMID 33072766, 2020).
atherosclerosis (continued). "In order to increase the knowledge about anthocyanins’ effects, it could be a good option to address together those age-related diseases, for example, using the apoE-deficient mouse—a widely used model of human atherosclerosis that has hyperlipidemia and develops all human atherosclerotic lesions." (PMID 32825684, 2020). "Pre-clinical studies using statins, which inhibit the HMG-CoA reductase to block cholesterol de novo synthesis, in ApoE-deficient mice revealed a marked regression of atherosclerosis through a CCR7-dependent emigration of foam cells from plaques supporting this hypothesis." (PMID 32411706, 2020). "Apolipoprotein E knockout (ApoE‐KO) mice have been shown to develop intracranial atherosclerosis; this approach is based on understanding of the plasma lipoprotein's role in cholesterol degradation and association with premature atherosclerosis in humans when deranged." (PMID 32613180, 2020). "The authors reported that APOE, a protein implicated in Alzheimer’s disease and in atherosclerosis, is expressed by microglia during development and has reciprocal receptors in neural cells, suggesting APOE may play an important and currently undefined role during neural development." (PMID 32630148, 2020). "Furthermore, the role of ER stress in atherosclerosis was highlighted using ApoE deficient mice (ApoE−/−) as a murine model for atherosclerosis, where the plaque size was reduced in aortas obtained from ApoE−/− mice treated with chemical chaperones to alleviate ER stress." (PMID 31319588, 2019). "We also observed that MCTs could ameliorate atherosclerosis in apoE-deficient (apoE−/−) mice." (PMID 31182969, 2019). "Similarly, ApoE-deficient mice develop severe hypercholesterolemia and atherosclerosis." (PMID 30354237, 2018). "Therefore, the aim of the present study was to determine whether oral administration of LPSp prevents the development of atherosclerosis in a high-fat diet (HFD)-induced model of atherosclerosis in apoE-deficient mice." (PMID 29584779, 2018). "Thus, the ApoE−/− pigs could be beneficial for delineating the underlying pathophysiology of hypercholesterolemia and atherosclerosis because their serum lipid profiles differ from existing pig models, which cannot sufficiently recapitulate human disease." (PMID 30305304, 2018). "Thus, phenotypes of inflammation and atherosclerosis reported in studies making use of HypoE mice and its derivatives could have been influenced through the expression of the Arg-61 apoE allele." (PMID 29789495, 2018). "However, whether the differential effects of inulin on atherosclerosis development in APOE-deficient mice versus E3L.CETP mice are mouse model-specific and/or a result of differences in dietary composition and/or housing conditions remain to be determined." (PMID 30409998, 2018). "Additionally, caspase-1 deficiency decreases atherosclerosis in apolipoprotein E-null mice." (PMID 29416034, 2018). "In addition, our lab has also demonstrated that xyloketal B has anti-atherosclerotic effects on APOE-deficient mice, suggesting that it may be a potential treatment agent for atherosclerosis." (PMID 28587208, 2017). "Additionally, it has been shown that allergic asthma may accelerate atherosclerosis via activation of Th2 and Th17 cells in apolipoprotein E deficient mice." (PMID 29073174, 2017). "In summary, this study demonstrated that moderate autophagy induced by low-dose rapamycin could alleviate atherosclerosis progression and promote plaque stability in the ApoE−/− mice model, which was associated with regulating VSMC autophagy and senescence by the mTORC1/ULK1/ATG13 signal pathway." (PMID 28713484, 2017).
atherosclerosis (continued). "Apolipoprotein E deficient (ApoE-/-) mice have been used to assess the effect of flavonoids on atherosclerosis, however the overall effect of the flavonoids, and the effect of individual classes of flavonoids on the severity of atherosclerosis remain unclear." (PMID 28742839, 2017). "Therefore, here we investigated the effect of cortistatin in two experimental models of acute and chronic atherosclerosis induced in apolipoprotein E-deficient (apoE−/−) mice fed a high-lipid Western diet, as well as the potential cellular and molecular mechanisms involved." (PMID 28406244, 2017). "Therefore, ApoE deficiency has been used extensively in experimental studies of atherosclerosis." (PMID 28688452, 2017). "Additionally, deletion of the IP receptor in atherosclerosis‐prone apolipoprotein E‐deficient mice significantly accelerates the development of atherosclerosis, which may be attributable, in part, to increased platelet reactivity." (PMID 26929147, 2016). "Moreover, we demonstrated that the Nox4-deficient ApoE KO mice exhibited significant protections against rFliC-mediated atherogenesis indicating that TLR5-dependent Nox4 activation is critical for the development of atherosclerosis." (PMID 27146088, 2016). "Future studies may uncover the dual role for monocytes in the development of atherosclerosis and arthritis in ApoE−/− mice and address the effects of ApoE deficiency on joint foam cell formation, IL-6 production and arthritis development in a cell-type specific fashion." (PMID 27287704, 2016). "Given the significance of angiogenesis and inflammation in AAA and atherosclerosis, we hypothesised that Angpt2 would be important in the development of AAA and atherosclerosis and examined this in the angiotensin II (AngII)-infused Apolipoprotein E deficient (ApoE−/−) mouse model." (PMID 27767064, 2016). "Indeed, PDGF-induced miR-221/222 upregulation followed by suppression of the cell cycle regulator p27Kip1 in VSMCs could contribute to atherogenesis because loss of p27Kip1 was reported to aggravate atherosclerosis in ApoE-deficient mice." (PMID 26221589, 2015). "Also, water restriction promoted atherosclerosis in aortic root and caused thickening of walls of coronary arteries in ApoE-/- mice, which is considered as a risk factor for development of atherosclerosis and predicts future clinical cardiovascular disease events.." (PMID 26042828, 2015). "In comparison, we previously found increased atherosclerosis but less pronounced alterations in serum lipid levels and lower body weight in male apoE-deficient ARKO mice fed an HFD; these discrepancies may be partly explained by developmental defects in male ARKO mice." (PMID 25550469, 2015). "In addition, inhibition of cholic acid synthesis by CYP8B1 deficiency inhibits dyslipidemia and atherosclerosis in ApoE−/− mice by decreasing intestinal lipid absorption, suggesting that cholic acid deficiency is caused by the lipid-lowering and anti-atherogenic effects of INT-767." (PMID 25237811, 2014). "Importantly, PPAR-γ agonist failed to reduce the atherosclerotic area in adiponectin-deficient mice under apolipoprotein E (ApoE) knockout background, suggesting that thiazolidinediones protect against atherosclerosis partly through its enhancing effect on adiponectin." (PMID 24884787, 2014). "Finally, we investigated atherosclerosis susceptibility in macCGI-58/ApoE-double KO (DKO) animals." (PMID 25316883, 2014). "Our recent study of PDCD4 and ApoE double-deficient mice (PDCD4−/−ApoE−/−) fed a high-cholesterol diet found that knockout of PDCD4 was associated with reduced atherosclerosis plaque areas (unpublished data), so PDCD4 downregulation might protect arteries against atherosclerosis." (PMID 24626527, 2014).
atherosclerosis (continued). "The ApoE deficient mouse is one of the best models as it provides great information, since these animals develop hypercholesterolemia spontaneously, with a cholesterol level up to five times higher than normal mice, developing atherosclerosis in a short period of time." (PMID 25328689, 2014). "Thus, CD40L and ApoE double deficient mice develop markedly reduced atherosclerosis." (PMID 24478772, 2014). "In addition, another study further demonstrated that RAGE could regulate atherosclerosis through adiposity by using RAGE apoE double deficient mice." (PMID 24575131, 2014). "The long-standing moderate-to-severe dyslipidaemia may suggest early atherosclerosis, but there is a surprising lack of signs of vascular damage in these patients, probably because of the raised apoE levels in the serum, counterbalancing the increased risk of atherosclerosis." (PMID 24683476, 2013). "Indeed, in apoE−/−mice (a model of human atherosclerosis), FcγRs appear to be important for the clearance of LDL-containing IC and apoE−/− mice deficient for the activating γ chain of FcγRs show less development and progression of atherosclerosis than apoE−/− mice which possess the γ chain of FcγRs." (PMID 23902799, 2013). "Taken together, these findings suggest that activation of eIF-2α signaling pathway is an underlying mechanism for the development of atherosclerosis in apoE−/− mice and that inhibition of this UPR pathway might provide a therapy strategy for treatment of atherosclerosis." (PMID 23984090, 2013). "Furthermore, APOE has also been found to be associated with increased atherosclerosis and CVD." (PMID 23613766, 2013). "C6 deficiency in apoE−/− mice, resulting in an inability to form C5b-9 complexes, resulted in more than a 50% decrease in atherosclerotic plaque area compared with control mice, therefore strongly supporting a functional role for C5-9 in progression of atherosclerosis." (PMID 24278688, 2012). "In contrast to the present results, a recent study showed that berberine can induce foam cell formation and promotes atherosclerosis development in apolipoprotein E-deficient (apoE-/-) mice, which could counter-balance the beneficial effect of lowering serum cholesterol." (PMID 22762542, 2012). "Considering that aging and atherosclerosis are risk factors for cardiac and neurovascular diseases, such as stroke, we investigated the regulation of arginase in young mice (1-month-old) and old mice (14-months-old) in a classical model of atherosclerosis, using ApoE−/− mice on a Western diet." (PMID 22709928, 2012). "However, it was recently reported that berberine promotes atherosclerosis development in apolipoprotein E-deficient (apoE-/-) mice, which could counter-balance the beneficial effect of lowering serum cholesterol." (PMID 22762542, 2012). "Hence it was tested whether partial inhibition of ACAT1 and ACAT2 (expressed in liver and intestine) activities reduces atherosclerosis development in apoE-deficient mice and avoids toxicity." (PMID 22934038, 2012). "The role of FXR in the initiation and progression of atherosclerosis has been studied in mice with Fxr gene ablation that were backcrossed into atherosclerosis-susceptible strains with either deletion of the low-density lipoprotein receptor or apolipoprotein E, respectively." (PMID 22187656, 2012). "Therefore, one must be cautious when interpreting these results because female apoE-/- mice may be more susceptible to developing endothelial dysfunction, as suggested by evidence showing that females are more prone to developing atherosclerosis than males." (PMID 22082357, 2011). "The similarities between atherosclerosis progression in humans and mice deficient either in apoE (apoE-/-) or the LDL receptor suggest that molecular mechanisms underlying regression in these mouse models could be relevant to the reduction in plaque burden in the human population." (PMID 22163030, 2011).